B2M (beta-2-microglobulin)
Diseases named in the same sentence as B2M in open-access papers (continued):
Sharing a sentence is not in itself a finding about the gene and the disease.
tumor (continued). "Subsequently, to verify the potential role of MHC-I in GC, MHC-I expression was inhibited byB2M knockdown.B2M knockdown significantly decreased MHC-I level and decreased CD8+ T-cell infiltration but promoted tumor size and weight." (PMID 38826133, 2024). "To further explore the role of B2M in RCC, we conducted qPCR and western blot analysis and found lower B2M expression in both murine Renca cells and human RCC tumor cells derived from distinct tissues of origin compared to normal kidney tissues/cells." (PMID 37526345, 2023). "To challenge the TILs, we deleted B2M by CRISPR/Cas9 (B2M KO) in a cell line from patient MM3, rendering the tumor cells resistant to the cytotoxic activity of autologous TILs but not to anti-HER2 CAR mRNA-transfected CAR-TILs." (PMID 36765608, 2023). "Mechanistically, αKG treatment decreases H3K4me1 in the promoter regions of B2M, thus upregulating MHC‐I expression and enhancing CTLs‐mediated anti‐tumor effects in multiple types of cancer including RCC." (PMID 37526345, 2023). "Tumoral cells often upregulate "Don't eat me" signals like CD47, programmed cell death ligand 1 (PD-L1), and B2M." (PMID 37822610, 2023). "Beta-2-microglobulin (B2M), an important subunit of MHC class I, has essential biological functions and roles in tumor immunity." (PMID 37842234, 2023). "High beta-2 microglobulin (B2M), LAG-3, CD25, and 4-1BB in tumor; high B2M, CD45, CD4 in stroma, and low fibronectin in the macrophage compartment, correlated with prolonged PFS." (PMID 37057033, 2023). "We explored tumor-infiltrating immune cells in COAD tumors from the TCGA cohort with different SCNAs in CIITA, HDAC2, and B2M." (PMID 37046620, 2023). "Upregulation of c-Myb in tumors resulted in enhanced expression of B2M, part of the MHC-I complex, suggesting that antigen presentation in these tumor cells is likely increased." (PMID 37478172, 2023). "Immune cell abundance study reveals that B2M and CD1D are both enriched in tumor cells and dendritic cells from patients responding to anti-PD1 immunotherapies." (PMID 37077920, 2023). "The median values of other tumor markers (Ferritin, A19-9, AFP, CEA, B2M) for the PanNEN patients with bone metastases and those in the non-bone metastatic group were also not significantly different (p > 0.05)." (PMID 37510802, 2023). "We have shown that PACAP is closely related to disease burden, as our results indicate that patients with active disease, higher plasma cell infiltration in bone marrow, higher tumor markers (LDH, B2M, BJ protein), and higher ISS stage have lower PACAP levels." (PMID 37445974, 2023). "Future research should address the outstanding question of how γδ T cells accumulate in B2M-deficient tumours, and whether the lack of CD8+ T cell activity might contribute to the establishment of an attractive niche for γδ T cells and other immune effector cells." (PMID 36631610, 2023). "Knockout of TRIM21 resulted in high expression of HLA-A, B2M, TAP1 and TAP2 in SUNE1 tumour cells isolated from BALB/c nude mice and of B2m, Tap1, Tap2, Tapbp and Earp1 in MC38 tumour cells isolated from C57BL/6 mice." (PMID 36797289, 2023). "In conclusion, we reveal an immunoregulatory circuit in which AKG inhibited RCC tumor growth by attenuating the enrichment of H3K4me1 in the promoter regions to upregulate B2M expression and enhance CD8+ T cell‐mediated anti‐tumor immunity." (PMID 37526345, 2023). "NGS results from EBV positive DLBCLs revealed the presence of recurrent alterations in B2M (6/9; 66.7%) and PTPN6 (3/9; 33.3%), which were related to the tumor microenvironment and JAK-STAT pathways, respectively." (PMID 36606194, 2022). "No significant changes in the expression of housekeeping genes, including beta-actin (ACTB), beta-2-microglobulin (B2M) and ubiquitin C (UBC), were detected in LUAD and UCEC tumor samples when compared to their respective normal samples." (PMID 36084949, 2022).
tumor (continued). "Beta-2-microglobulin (β2M), an important subunit of major histocompatibility complex (MHC) class I, has important biological functions and roles in tumor immunity." (PMID 36046045, 2022). "MHC class I is expressed by all nucleated cells and, together with the beta-2-microglobulin chain, plays a crucial role in cancer immunosurveillance resulting in peptide MHC class I recognition on tumor cells by cytotoxic T cells." (PMID 35892842, 2022). "Beta 2 microglobulin (B2M) is essential for MCH I function and presentation of antigen to T cells by tumour cells." (PMID 35054292, 2022). "B2M, as a crucial ingredient of MHC class I–mediated antigen presentation by tumor cells, has been announced to be presented in immune cells." (PMID 36339715, 2022). "When the clinical responses were evaluated according to the results from APM biomarker analyses, only one case presented with a tumor that had normal expression of the investigated APM biomarkers (i.e., HLA class I and B2M)." (PMID 36615128, 2022). "Specifically, CCND1 amplified tumor tissues exhibited decreased mRNA expression of CD8, Gzm, B2m and Tap1 and significantly lower proportions of CD8 T cell and T follicular helper cells." (PMID 35844619, 2022). "Strikingly, a large proportion of the IFNγ signature genes were upregulated by SHP2 inhibition specifically in tumor cells in co-culture, including cytokines (CXCL9, CXCL10, CXCL11 and CCL5) and antigen presenting machinery (HLA-A, HLA-B and B2M)." (PMID 33446805, 2021). "A striking feature of KRAS KO tumor cells was a significant 2–10-fold increase in MHC gene expression (H2d1, H2k1, B2m, and H2-aa, H2-ab1, CD74) over KRAS intact controls." (PMID 33674596, 2021). "Three genes, including B2M, FGF9 and HMGA1, were also found in the 30 upregulated (in tumor MF) gene list." (PMID 34831413, 2021). "For that, prospective trials with larger patient cohorts recording metastatic patterns and B2M mutation status are required, which shall reveal whether the good survival of B2M-mutant M1 MSI cancer patients under ICB reflects the biology of the tumor cells, or indicates treatment response." (PMID 34168989, 2021). "Double-knockout (TRAC and B2M) and triple-knockout (TRAC, B2M and PD-1) CAR-T cells via CRISPR/Cas9 technology showed superior anti-tumor activity." (PMID 35111663, 2021). "In order to study the molecular mechanism of CALR involved in tumor progression, we used String and GeneMANIA databases finding that PDIA3, B2M, GANAB, CANX, and TAPBP interact with CALR." (PMID 34910788, 2021). "B2M is a prognostic marker for MCL and serves as an indicator of MCL tumor burden in mouse PDX models." (PMID 34001881, 2021). "Therefore, the genetic deficiency of B2M may cause a lack of tumor cell recognition by T cells because of the loss of MHC class I folding and transport to the cell surface." (PMID 35582437, 2020). "The basal tumor cluster #3 demonstrated transcriptional downregulation of HRAS; cell dormancy; and a higher expression of IGFBP7, MDK, and B2M, recapitulating those of the tipifarnib-resistant (or cluster B) BC159-T#3 PDX tumor cells." (PMID 32460812, 2020). "In the growing tumor area, FADS1, FADS2, SCD, and SCD5 expression positively correlated when using the B2M gene as reference." (PMID 32392704, 2020). "A proposed strategy for rescuing defective B2M expression involves administration of an adenoviral vector expressing B2M, which in tumor cell lines has been shown to recover MHC-I expression, and tumor cell destruction by CD8+ T-cells." (PMID 33260693, 2020). "Using the B2M gene as reference, the expression of SCD in the peritumoral area was more than 5 times higher (p = 0.005) than in the growing tumor area." (PMID 32392704, 2020).
tumor (continued). "Several markers significantly correlated with CD3 expression in the tumour compartment, including CD40, CD44, CD14, B2M, Tim-3, CD8, CD45RO, and ICOS, potentially implicating other cell lineages in immune-associated anti-tumour activity." (PMID 33261133, 2020). "The process of hiding the tumor identity involves major histocompatibility complex (MHC) I-related genes (e.g., HLA-A/B/C, TAP1/2, TAPBP, and B2M)." (PMID 31737562, 2019). "Conversely, loss of staining in tumours with wild‐type B2M might be due to large genomic rearrangements not identifiable with Sanger sequencing, promoter mutations, mutations involving miRNA recognition sites, low neoplastic cell content (<20%) or sampling error." (PMID 31062389, 2019). "Although we found a few small lesions that lost the expression of HLA and B2M in the relapsed tumor from JFCR-119, both HLA and B2M were widely positive in the pretreatment tumor and in the majority of post-treatment tumor lesions." (PMID 30872362, 2019). "Overall, despite variations in the expression levels of B7-H3, B7-H4, B2M, and CK7 among the two resections from the same patient, the positivity of these markers was conserved in the tumor cells of all patients over time." (PMID 31692889, 2019). "Among different types of tumor markers, protein biomarkers, such as IMP2, AFP, B2M, CA15-3, CA19-9, CA-125, cytokeratin and so on, are especially welcomed due to its accessibility." (PMID 30755649, 2019). "In addition, The second most stable gene, B2M, encodes β2-microglobulin, which has not been cited by GWAS as a potential gene involved in OP, however, previous studies related its association with bone metabolism in tumor processes." (PMID 31712560, 2019). "We propose that B2M testing is a useful adjunct to routine MMR testing and should be incorporated into a bowel tumour‐specific assay in conjunction with MLH1, KRAS, NRAS and BRAF status to provide an overall recurrence risk for individual patients." (PMID 31062389, 2019). "In conclusion, our study implied the potential role of MSCs-derived B2M in the ESCC development and further confirmed the reciprocity between MSCs and tumor." (PMID 29615660, 2018). "In this study, we revealed that MSCs-derived B2M significantly induced epithelial-to-mesenchymal transition (EMT) in ESCC cells, and observed its subsequent enhancing effects on cell mobility and tumor-initiation." (PMID 29615660, 2018). "Although only B2M alterations were exclusively present in non-responders within our cohort, the mutations observed in the interferon pathway may also contribute to immune evasion by tumor populations in response to CPB." (PMID 29070816, 2017). "When normalized with respect to the housekeeping genes B2M or GAPDH, mean tumor/normal ratios were 16.1 and 7.5, respectively." (PMID 24383454, 2014). "There was a significant correlation between tumour surface area and faecal expression of COX-2 mRNA, B2M mRNA, and CEA mRNA in CRC patients." (PMID 20145612, 2010). "Analysis of tumors from ApcMin/+/Ptpn13fl/fl/Vil-CreERT2 (APV) mice showed that Ptpn13 knockout, induced by TAM treatment, significantly upregulated the expression of IRF1, LMP2, TAP1, TAP2, H2-D1, H2-K1, and B2M and also increased the surface levels of MHC-I complex on tumor cells." (PMID 41486293, 2026). "Beta-2 microglobulin (B2M), the light chain of major histocompatibility complex (MHC) class I, plays an indispensable part by presenting tumor antigens to cytotoxic T lymphocytes (CTLs) for exerting anti-tumor effects." (PMID 40191187, 2025). "Organs from an egg without a tumor were used to test eight primers for cross‐reactivity with the chicken cells, namely B2M, HMBS, ALTB, TBP, SDHA, YWHAZ, and UBC." (PMID 40443053, 2025).
tumor (continued). "Only when both cDC1s and cross-dressed inflammatory monocytes were absent (B2m KO tumours engrafted into Rag2–/–Batf3–/– mice) did T cells fail to become restimulated." (PMID 39604727, 2025). "Preliminary experiments indicated an increase in the CD8/CD4 ratio and a two-fold increase in the expansion capacity of CAR-T cells without tumor stimulation when B2M and CIITA were knocked down." (PMID 39856752, 2025). "Notably, VSIG4 knockout recovered the expression of antigen-presentation genes (H2-K1, B2m, and H2-D1) in TAMs, and targeting VSIG4+ TAMs significantly promoted the tumor infiltration and proliferation of antigen-specific CD8+ T cells." (PMID 39920772, 2025). "The DEGs including H2-K1, B2m, and H2-D1 in VSIG4-KO TAMs were significantly upregulated and related with anti-tumor signals containing positive regulation of the innate immune response, T cell-mediated cytotoxicity against tumor cells, and antigen-presenting and presentation via MHC I." (PMID 39920772, 2025). "Allografted tumors were established using the B2M KO lines in wild type C57BL/6 mice and these tumor models were utilized to evaluate the efficacy of mIL12 mRNA in experiments analogous to the unmodified Yummer 1.7 and MC38 parental tumor models." (PMID 40321762, 2025). "These include well-known tumor markers (e.g., CA19-9, CEA, and CA125), as well as proteins more recently described as potential novel biomarkers for the detection of PC (e.g., Beta-2 microglobulin (B2M), TIMP-1, CRP, Galectin-3, uPA, and VEGF-A)." (PMID 40563629, 2025). "B2M is a crucial molecule indispensable for the assembly of MHC-I complexes and tumor antigen presentation, and its defect might be a prevailing cause of resistance to ICIs therapy." (PMID 40191187, 2025). "Statistically significant differences were observed, with higher initial and final beta-2 microglobulin levels in MF patients with neoplasms compared to those without (p = 0.002, 0.005)." (PMID 40524021, 2025). "Indeed, both the recruitment of EZH2 to the promoter regions of B2m and H2Kb and their H3K27me3 modification levels, was decreased in USP22-null tumor cells." (PMID 41252204, 2025). "Furthermore, the expression of B2M, a key subunit of the MHC‐I complex, was also elevated in I3A‐treated tumor cells." (PMID 40583248, 2025). "We surmise that the large non-fluorescent tumor foci originated from tumor cells without TSPY co-integration/expression with the oncogenes while those fluorescent ones expressed TSPY but lacked B2M protein, essential for peptide-MHC-I complex formation." (PMID 40563082, 2025). "CD8+ memory T cells can recognize and destroy tumor cells with no TAP or beta-2 microglobulin (β2M) at all, driven by Sec62-mediated import of peptides into the ER and chaperone-facilitated stabilization of free MHC-I heavy chains." (PMID 41293269, 2025). "We observed consistently higher expression levels of MHC class I genes (HLA-A, HLA-B, HLA-F, HLA-E, B2M) in tumor cells from non-progressors to progressors." (PMID 39753553, 2025). "B2M expression extended beyond the areas of tumor attrition, and CD8+ T cells localized with it, nonspecific to tumor attrition sites." (PMID 41109214, 2025). "In comparison, only one MSI-H tumour was identified in the New EPOC in a non-encapsulated patient (p = 0.54), and for both B2M and PTEN only two pathogenic mutations were present, one in each growth pattern phenotype (both q = 0.80)." (PMID 40702107, 2025). "Since B2M encodes for a protein vital for the structural integrity of MHC Class I complexes, any non-functional B2M subunits would disrupt the presentation of tumor antigens to Cytotoxic T cells." (PMID 41415395, 2025). "We also analyzed protein factors released in the supernatants of US-treated cancer cells, detecting well-known tumor markers (e.g., CA19-9, CEA, and CA125), as well as proteins as candidate novel biomarkers for the detection of PC, particularly B2M, CRP, TIMP1, and Galectin-3." (PMID 40563629, 2025).
tumor (continued). "While TET2 ChIPs at the B2M promoter, its loss only weakly reduces B2M expression in B16 cells and does not reduce B2M tumor expression as measured through flow cytometry, indicating a role for additional actors in promoting B2M gene expression." (PMID 39388288, 2024). "Our data showed that B2M expression was strongly associated with CD8A expression in the multiple probes (0.9<R<0.93) not in the tumor cells, but in cancer str of the CRC tumors." (PMID 38557819, 2024). "We found several molecules that are significant in tumor initiation and treatment by immune checkpoint analysis, such as lymphocyte-activation gene 3 (LAG3), PTPRC, HAVCR2, B2M, LDHA, and LDHB, which may be used as a reference for tumor immunotherapy." (PMID 39014082, 2024). "B2M, a vital component of the major histocompatibility complex (MHC) class I molecules, is crucial in antigen presentation to CD8+ T cells and in modulating the immune response against tumor cells." (PMID 38455061, 2024). "Compared to wt EMT6, the absence of B2m or LMP2 protein expression on tumor cells resulted in a significant reduction of M-MDSCs and PMN-MDSCs in the TME, with Jak1 deletion only decreasing the former." (PMID 38427670, 2024). "Across all the tumor types, metastatic samples were approximately 2.5 times more likely to be B2M negative compared to primary tumor samples (Odds ratio ~ 0.39 [CI 0.18 - 0.81], p-value ~ 0.012)." (PMID 38455061, 2024). "Immunosuppressive macrophage signaling is also implicated in the development of antiphagocytic signaling within tumor cells, which is regulated by overexpression of CD47, PD-L1, and beta-2-microglobulin, and allows tumors to avoid macrophage dependent phagocytosis." (PMID 39612029, 2024). "However, and in contrast to EMT6 B2m KO tumors, deletion of B2m on MC38 tumor cells resulted in significant reduction of macrophage, DC, and CD8+ T cells in the TME." (PMID 38427670, 2024). "We observed complete tumor regression in PDX mice from tumors that lacked B2M and were treated with CAR-TILs (but not TILs)." (PMID 36765608, 2023). "Following CD4+ T cell stimulation, CD8+ cytotoxic lymphocytes (CTLs) activate the T cell mediated immune response, resulting in the killing of tumour cells, as a result of the interaction between TCR molecules and the MHC class I complex αβ dimer and β2 microglobulin (B2M)." (PMID 36980527, 2023). "Next, we evaluated whether B2M, CD1D, and CD1B differential expression are impacted at the tumor cells or DCs levels in the TME." (PMID 37077920, 2023). "We analyzed CNV data of paired normal and tumor WES generated using the Sequenza pipeline in the context of the MAPPYACTS study for the chromosome arms 6p (HLA region), 15q and 16p (containing the B2M and CIITA genes, respectively)." (PMID 38318504, 2023). "We next tested the association of primary/metastasis-specific downregulation of an MHC class I metagene signature composed of a composite expression of HLA-A, HLA-B, HLA-C, B2M, TAP1, TAP2 and NLRC5 between metastasis and matched primary tumor according to intrinsic subtype." (PMID 36585450, 2023). "APM biomarker analyses was only conducted for this tumor to elucidate reasons for this development, and lack of HLA and B2M protein expression was found on the tumor cells." (PMID 36615128, 2022). "Therefore, B2M gene dysfunction played a crucial role in impairing MHC class I assembly and HLA cell surface expression, which helps tumor cells escape from the recognition by cytotoxic T cells." (PMID 36606194, 2022). "HLA class I components were downregulated in the treated tumours, specifically HLA I heavy chain and B2M, rendering the tumours resistant to ICB without any prior exposure to this type of treatment." (PMID 36476325, 2022). "Therefore, we co-cultured tumor-activated alloreactive T cells with matched A375, 786-O or A549 cells, and corresponding tumor cells with downregulated HLA-I after TAP or B2M gene knockout." (PMID 36612246, 2022).